SNORD114-1 (small nucleolar RNA, C/D box 114-1)
Synonyms: 14q(II-1)
Gene: Small nucleolar RNA gene on chromosome 14 (100,949,833 to 100,949,904, forward strand). Ensembl gene ENSG00000199575.
Gene Ontology:
Biological process: RNA processing
Cellular component: nucleolus
Homologues: Orthologues: chimpanzee SNORD114-1 (99% identical), macaque SNORD114-1 (96% identical), mouse Gm23736 (69% identical), rat Snord113l1 (68% identical), mouse Gm22981 (65% identical), rat LOC120093391 (65% identical), mouse AF357341 (64% identical), mouse AF357428 (61% identical), mouse Gm25856 (56% identical). Paralogues in human: SNORD114-3 (86% identical), SNORD114-23 (85% identical), SNORD114-11 (83% identical), SNORD114-2 (82% identical), SNORD114-21 (82% identical), SNORD114-26 (82% identical), SNORD114-15 (81% identical), SNORD114-18 (81% identical), SNORD114-20 (81% identical), SNORD114-25 (81% identical), SNORD114-28 (81% identical), SNORD114-6 (81% identical), and 26 more.
Diseases named in the same sentence as SNORD114-1 in open-access papers:
SNORD114-1 is named in the same sentence as 5 diseases in open-access papers, as found by Europe PMC text mining. Sharing a sentence is not in itself a finding about the gene and the disease. The quoted sentences say what the papers report.
acute leukemia (1 paper, 2015). A clonal (malignant) hematopoietic disorder with an acute onset, affecting the bone marrow and the peripheral blood. "Thus, the levels of snoRNAs are elevated in non-small-cell lung cancer (NSCLC), acute leukemias, and metastatic prostate cancer, and individual snoRNAs have been shown to contribute to cellular proliferation and/or transformation (SNORD114-1 in K562 cells, SNORA42 in breast cancer)." (PMID 25888729, 2015).
SNORD114-1 also shares sentences with these, for which no sentence is quoted: breast carcinoma (1 paper); leukemia (1); metastatic prostate carcinoma (1); non-small cell lung carcinoma (1).